IRF4 (interferon regulatory factor 4)
Diseases named in the same sentence as IRF4 in open-access papers (continued):
Sharing a sentence is not in itself a finding about the gene and the disease.
hematologic malignancies (12 papers, 2014 to 2026). "Previous studies have shown that abnormal IRF4 expression can be used as a diagnostic and prognostic marker for various hematologic malignancies." (PMID 35983077, 2022). "The co-identification of variants in IRF4 associated with the risk for both myeloid and lymphoid malignancy supports the importance of broader studies that span the spectrum hematologic malignancies." (PMID 34220922, 2021). "In contrast, our recent studies have shown that LIMD1 plays a pro-oncogenic role in hematological malignancies in association with the oncogenic transcription factor interferon regulatory factor 4 (IRF4)." (PMID 33869018, 2021). "In this study, we aim to profile IRF4-associated unique molecular signatures in different types of hematological malignancies, by analyzing existing gene expression profile databases obtained from clinical samples." (PMID 25207815, 2014). "In clinical practice, IRF4 serves as an important prognostic and diagnostic marker for certain types of hematological malignancies." (PMID 25207815, 2014). "The functional significance of variants in this gene in hematopoiesis and its previous recognition as a locus associated with the risk for development of other hematological malignancies, further strengthen the evidence of an association of IRF4 with development of AML and MDS." (PMID 34220922, 2021). "With our identification of vIRF3 as an IRF4 co-TF, it is apparent that each of the three human viruses linked to hematologic malignancy (EBV, KSHV, and HTLV-1) encodes at least one protein that usurps IRF4 and/or BATF family members to promote the survival and proliferation of infected cells." (PMID 32843547, 2020). "Increasing evidence has implicated IRF4 in hematological malignancies." (PMID 25207815, 2014). "Interferon regulatory factor 4 (IRF4) is involved in the pathogenesis of various hematologic malignancies." (PMID 34952638, 2021). "First, a pool of gene expression profile datasets obtained from different types of hematological malignancies were analyzed for genes whose expression is correlated with IRF4 using the Oncomine website." (PMID 25207815, 2014). "In recent years, we have employed multiple omics approaches, including microarray, ChIP-seq, phosphoproteomics, and secondary analyses of high-throughput data, to identify IRF4 transcriptional targets and elucidate its functions in hematological malignancies and other biological settings." (PMID 40733503, 2025). "We have previously shown that LIMD1 expression correlates with IRF4 in hematological malignancies, suggesting that LIMD1 may be transcriptionally regulated by IRF4." (PMID 29464072, 2018). "The implication of IRF4 in hematological malignancies is increasingly recognized." (PMID 25207815, 2014). "These lines of evidence highlight the importance of IRF4 in hematological malignancies." (PMID 25207815, 2014). "Likewise, blockade of STAT3 with small-molecule inhibitors such as JQ1 diminishes IRF4-associated transcriptional modules in lymphocytes and myeloid cells, while BET bromodomain inhibitors such as I-BET762 downregulate IRF4 expression and IRF4-driven inflammatory genes in hematologic malignancies." (PMID 41614922, 2026). "We and others have shown that IRF4 promotes proliferation of EBV-transformed cells and IRF4 deficiency results in death of cells derived from different hematological malignancies, indicating that IRF4 plays a non-redundant role in tumorigenesis of hematological malignancies." (PMID 25207815, 2014).
hematological cancer (6 papers, 2014 to 2025). "IRF4 chromosomal translocation/mutation was mainly associated with hematopoietic cancers and found in particular in multiple myeloma, large B-cell lymphoma, and adult T-cell lymphoma-leukemia." (PMID 37809068, 2023). "Accordingly, our data support an oncogenic function for IRF4 in NK-cells, thereby extending the transforming capacity of this gene in hematological cancers." (PMID 28977998, 2017).
bacterial infection (3 papers, 2023 to 2025). "Here, we use mouse models for intestinal nematode infection (Strongyloides ratti) and intestinal bacterial infection (Citrobacter rodentium) to analyze the Th2 and Th17 cell responses of Irf4-deficient CD4+ T cells." (PMID 37469513, 2023). "In conclusion, these results demonstrate that IRF4 is required for intestinal Th17 cell responses to oral bacterial infection." (PMID 37469513, 2023).
blood cancers (3 papers, 2022 to 2025). "To test whether enforced FOXO1 expression is sufficient to induce EBF1, IRF4, or PAX5 expression in non-B-lineage blood cancer cells, we next transduced lentivirus encoding FOXO1 into the AML cell lines HEL and THP1, which express negligible levels of EBF1, FOXO1, IRF4, and PAX5." (PMID 36282572, 2022).
immune diseases (3 papers, 2017 to 2025). "IRF4, as an essential controller of Th17 differentiation, participates in many immune diseases." (PMID 28808358, 2017).
inflammation (3 papers, 2018 to 2023). Aberrant reaction of the microcirculation characterized by movement of fluid and leukocytes from the blood into extravascular tissues. "In an allergic airway disease model, deletion of IRF4 expression in CD11c+ cells attenuated Th2-type lung inflammation, and IRF4 was found to directly modulate IL-10 and IL-33 production by DCs, promoting Th2 differentiation and inflammation." (PMID 29343807, 2018). "We have previously shown that repeated administration of MDP lowers expression of inflammatory markers in adipose tissue of obese male mice, but adipose inflammation was not altered by MDP in obese male mice with a whole‐body deletion of IRF4." (PMID 35993451, 2022).
kidney disease (2 papers, 2019 to 2022). "Certainly, the fundamental proof for a causative role of IRF4-deficient M1-primed macrophages in the chronic inflammatory phase of renal disease could be answered using conditional and cell-specific knock-out mice." (PMID 31632388, 2019). "Furthermore, they highlight the importance of IRF4 in mediating kidney injury and identify it as a potential target for the future development of novel therapies for kidney disease." (PMID 35025763, 2022). "Lastly, we evaluated IRF4 and M1/M2-phenotypic marker expression in tubular human renal biopsy specimens with different CKD stages and renal diseases to examine the transferability of our results to human disease." (PMID 31632388, 2019).
colon (1 paper, 2020). "Overall, histopathologically assessed parameters summarized in the histology score underscore and further extend the results obtained during endoscopic evaluation that Rag1−/− mice lacking IRF4 expression are largely protected from T cell mediated colon inflammation." (PMID 33584655, 2020).
kidney (1 paper, 2022). "We examined if protective effects of IRF4 deletion persisted into the chronic kidney injury phase by studying a different group of macrophage IRF4–/– mice and controls 4 weeks after repeated AA injections." (PMID 35025763, 2022). "Our IRF4-knockout model specifically targets macrophages and resulted in reduced injury due to inhibition of macrophage migration to the injured kidney, highlighting the importance of the myeloid lineage in AA-induced kidney injury." (PMID 35025763, 2022).
myopathy (1 paper, 2020). A disease of the muscle in which the muscle fibers do not function properly. "Mice lacking interferon regulatory factor 4 (IRF4) in BAT (BATI4KO) exhibit reduced exercise capacity at both low and high-intensity treadmill running, and display selective myopathy." (PMID 32265830, 2020).
neurological diseases (1 paper, 2014). "Using genetic manipulations, we showed that IRF4-TG mice displayed reduced infarct lesions and improved neurological deficits; conversely, IRF4 deficiency rendered the mice more prone to I/R-induced brain damage and neurological disorders." (PMID 24510125, 2014).
IRF4 also shares sentences with these, for which no sentence is quoted: multiple myeloma (73 papers); Allergy (4); adult T-cell leukemia/lymphoma (3); atherosclerosis (3); actinic keratosis (2); adenocarcinoma (2); basal cell carcinoma (2); Central Nervous System Lymphoma (2); clear cell renal carcinoma (2); dermatitis (2); endotoxemia (2); esophageal squamous cell carcinoma (2); infectious disease (2); malignant neoplasms of the prostate (2); marginal zone lymphoma (2); multiple sclerosis (2); oral squamous cell carcinoma (2); plasma cell disorder (2); plasmacytoma (2); small cell lung carcinoma (2); type 2 diabetes (2); ulcerative colitis (2); vitiligo (2); Waldenström’s macroglobulinemia (2); acne (1); alopecia (1); ankylosing spondylitis (1); Arrhythmia (1); Arthralgia (1); atopic dermatitis (1).
A further 70 diseases each share a sentence with IRF4 in 1 paper.